ENSG00000275266
Gene: Miscellaneous RNA gene on chromosome 11 (1,996,540 to 1,996,610, forward strand). Ensembl gene ENSG00000275266.
Homologues: Orthologues: mouse Gm56420 (92% identical).